XIAP (X-linked inhibitor of apoptosis)
Diseases named in the same sentence as XIAP in open-access papers (continued):
Sharing a sentence is not in itself a finding about the gene and the disease.
cervical carcinoma (28 papers, 2004 to 2026). A carcinoma arising from either the exocervical squamous epithelium or the endocervical glandular epithelium. "XIAP, an apoptosis inhibitor directly restraining the caspase activity, exhibits an apoptosis inhibitory function in cervical cancer cells because its deficiency leads to upregulated cleaved caspase-3 and PARP1 protein levels." (PMID 39408613, 2024). "The inhibition of some IAPs, including the X-linked inhibitor of apoptosis protein and survivin has been reported to have therapeutic potential or a prognostic value for cervical cancers." (PMID 26748613, 2016). "Furthermore, research indicates that triptolide can also induce cuproptosis, presenting a novel antitumor strategy for cervical cancer by specifically targeting the X-Linked inhibitor of apoptosis (XIAP)." (PMID 39949740, 2025). "This is in contrast with a previous study reporting the importance of enhanced cleavage of XIAP for increased rhTRAIL-induced apoptosis mediated by proteasome inhibitor MG132 in cervical cancer cells." (PMID 41180258, 2025). "In summary, we report a new antitumor mechanism by which triptolide disrupted intracellular copper homeostasis and induced cuproptosis in cervical cancer by regulating the XIAP/COMMD1/ATP7A/B axis." (PMID 39198750, 2024). "Our study clarifies that MCPIP1 promotes cervical cancer cell apoptosis by suppressing the expression of XIAP, thereby impeding cervical cancer progression." (PMID 39408613, 2024). "In summary, we report a new antitumor mechanism of triptolide, which disrupted intracellular copper homeostasis and induced cuproptosis in cervical cancer cells by regulating the XIAP/COMMD1/ATP7A/B axis." (PMID 39198750, 2024). "In line with our findings, the XIAP‐downregulating effect of bufotalin has been previously identified in cervical cancer cells." (PMID 38044583, 2024). "Here, we revealed the key connection between XIAP and copper homeostasis in triptolide-treated cervical cancer cells." (PMID 39198750, 2024). "As a result, XIAP’s protein expression is suppressed in cervical cancer cells, leading to increased cell apoptosis and impediments to cervical cancer development." (PMID 39408613, 2024). "Our study would clarify that MCPIP1 promotes cervical cancer cell apoptosis by suppressing the expression of XIAP, thereby impeding cervical cancer progression." (PMID 39408613, 2024). "We demonstrated that triptolide upregulated COMMD1 expression and downregulated ATP7A and ATP7B expression by inhibiting XIAP, thereby promoting intracellular copper accumulation and subsequently inducing cuproptosis in cervical cancer cells." (PMID 39198750, 2024). "In cervical cancer, XIAP were demonstrated to directly bind to C-RAF which belongs to the Ras effector proteins (part of the MAPK cascade) and resulted in conformational change of C-RAF." (PMID 31548877, 2019). "In this study, we observed that EM23, a natural SL, exhibited anti-cancer activity in human cervical cancer cell lines by inducing apoptosis as indicated by caspase 3 activation, XIAP downregulation and mitochondrial dysfunction." (PMID 26758418, 2016). "In this study, we report that B5 induces apoptosis in two human cervical cancer cell lines, CaSki and SiHa, as evidenced by the downregulation of XIAP, activation of caspases and cleavage of PARP." (PMID 26439985, 2015). "Blockade of autocrine TGF-β signaling in KLE endometrial carcinoma cells and HeLa cervical cancer cells reduced endogenous XIAP mRNA and protein levels." (PMID 20712893, 2010). "In cervical cancer, we have recently shown that XIAP and survivin are overexpressed and that XIAP levels correlate with relapse of this disease." (PMID 17067390, 2006). "In the present study we investigate the expression of c-IAP1, c-IAP2, XIAP and survivin and its isoforms in cervical cancer." (PMID 16504151, 2006). "This is highly unlikely, since low XIAP mRNA is a marker for earlier recurrence in cervical cancer patients." (PMID 17067390, 2006).
cervical carcinoma (continued). "Conflicting observations, however, have been reported between XIAP expression and tumour stage or patient's survival in carcinomas of the cervix as well as non-small-cell lung carcinomas of early or advanced stages." (PMID 15328523, 2004). "Therefore, our research findings propelled us to conclude that XIAP mediates the apoptosis regulatory role of MCPIP1 in cervical cancer cells." (PMID 39408613, 2024). "Then, we addressed the function of XIAP in cervical cancer cell apoptosis." (PMID 39408613, 2024). "Our study identified XIAP as a target of MCPIP1 in exerting its apoptosis-promoting role in cervical cancer cells, which was supported by the findings that the forced expression of XIAP could reverse the pro-apoptotic effect of MCPIP1 on cervical cancer cells." (PMID 39408613, 2024). "Mature 5p strand of miR-7 is down-regulated in cervical cancer versus normal tissue and its overexpression inhibits the Focal Adhesion Kinase (FAK) and X-Linked Inhibitor of Apoptosis (XIAP) oncoproteins formation inducing apoptosis, inhibiting proliferation, migration and invasion." (PMID 28216603, 2017). "Two model cancer cell lines (KLE endometrial carcinoma cells and HeLa cervical cancer cells) and pharmacological inhibitors were used to investigate the signalling pathways regulating XIAP expression and activity in response to autocrine and paracrine TGF-β in cancer cell." (PMID 20712893, 2010). "In cervical cancer, ZC3H12A binds to XIAP mRNA via its ZF domain and promotes its degradation through its PIN domain RNase activity, thereby inducing apoptosis via the XIAP/caspase/PARP1 pathway." (PMID 41154702, 2025). "In this study, we reported a new antitumor mechanism by which triptolide promotes intracellular copper accumulation by regulating the XIAP/COMMD1 pathway and subsequently induces cuproptosis in cervical cancer cells." (PMID 39198750, 2024). "We also infected the cervical cancer cells with a lentivirus of MCPIP1 shRNAs and determined the XIAP’s mRNA levels by RT-qPCR analysis." (PMID 39408613, 2024). "In the present study, we analyzed the expression of XIAP, survivin and its isoforms, c-IAP1 and c-IAP2 by means of RT-PCR assays in cervical cancer samples." (PMID 16504151, 2006). "Our Western blotting assay demonstrated that XIAP knockdown in HeLa and SiHa cells led to increased expression of cleaved caspase-3 and cleaved PARP1, verifying its apoptosis-resistant function in cervical cancer cells." (PMID 39408613, 2024). "Since both XIAP and survivin are overexpressed in cervical cancer, the level of Smac/DIABLO expression should depend not only on mRNA expression, but also on the balance between these proteins and the release from mitochondria." (PMID 17067390, 2006). "However, if cervical cancer cells were co-infected with a lentivirus of MCPIP1 and XIAP, XIAP overexpression could attenuate the increase in cleaved caspase-3 and cleaved PARP1 protein activated by MCPIP1 overexpression." (PMID 39408613, 2024). "Consequently, C306R does not affect the mRNA or the protein expression level of XIAP in cervical cancer cells, which differs from MCPIP1." (PMID 39408613, 2024). "The Western blotting results showed that MCPIP1 but not C306R overexpression reduced the protein levels of XIAP but increased cleaved caspase-3 and cleaved PARP1 in cervical cancer cells." (PMID 39408613, 2024).
gastric cancer (26 papers, 2009 to 2025). A primary or metastatic malignant neoplasm involving the stomach. "MiRNAs encoded by the miR-200bc/429 cluster has also been found to function as inhibitors of ADR- resistant gastric cancer cells through inhibiting expression of Bcl-2 and X-linked inhibitor of apoptosis (XIAP)." (PMID 32192494, 2020). "Overexpression of X-linked Inhibitor of Apoptosis (XIAP) has been shown to be associated with activated AKT in many cancers including gastric cancer." (PMID 30096805, 2018). "XIAP is an important target for treatment because of its increased expression in gastric cancer patients." (PMID 31699976, 2019). "One important finding of this study is that XIAP downregulation is essential for CBD-induced apoptosis in gastric cancer cells." (PMID 31699976, 2019). "In conclusion, our study showed that CBD induces apoptotic cell death in gastric cancer cells, which is triggered by ER stress generation and subsequent XIAP inhibition by Smac." (PMID 31699976, 2019). "In this study, we reported that CBD also induced apoptosis by regulating Smac/XIAP through mitochondrial dysfunction in gastric cancer for the first time." (PMID 31699976, 2019). "The molecular mechanism of CBD action involves the induction of ERS and mitochondrial dysfunction by translocating the proapoptotic factor Smac to the cytoplasm to bind to the X-linked inhibitor of apoptosis protein (XIAP), thereby increasing the ubiquitination of XIAP in gastric cancer cells." (PMID 38731434, 2024). "The inhibitors of apoptosis proteins, XIAP and survivin, were decreased by evodiamine, which might be involved in the activation of caspases after evodiamine treatment in gastric cancer cells." (PMID 36135210, 2022). "Using Human apoptosis antibody array, we found that NDUFC1 knockdown may promote gastric cancer cell apoptosis through downregulating Bcl-2, clAP-2, Survivin, sTNF-R1, and XIAP." (PMID 34966665, 2021). "Thus, we excluded the role of XIAP in TP/TNF-α–induced apoptosis in gastric cancer and supposed that FLIP might play an essential role in TP/TNF-α–induced apoptosis in AGS and MKN45 cells." (PMID 36110523, 2022). "In gastric cancer, LINC02139 modulated cell proliferation and apoptosis by interacting with and stabilizing XIAP through blocking its ubiquitination." (PMID 40641925, 2025). "In gastric cancer cell lines (AGS 4 μM, MKN45 10 μM), CBD regulated Smac and XIAP expression through mitochondrial dysfunction and ER stress." (PMID 40006844, 2025). "Triptolide can promote apoptosis by inhibiting XIAP in U937 cells, AML cells, KB cells,and gastric cancer cells." (PMID 39198750, 2024). "Another study demonstrated the ability of CT to potentiate the antitumor effects of doxorubicin on gastric cancer cells through down regulation of STAT3 target genes such as Bcl-xL, Mcl-1, surviving and XIAP." (PMID 33544704, 2021). "Our results show that CBD induces mitochondrial dysfunction and regulates Smac/XIAP leading to apoptosis, suggesting that Smac/XIAP regulation using CBD can be potentially utilized for the treatment of gastric cancer." (PMID 31699976, 2019). "To determine the effect of the survivin inhibitor YM155 on the expression of survivin and XIAP, another member of the IAP family, we performed Western blotting in pancreatic and gastric cancer cell lines." (PMID 22723871, 2012).
gastric cancer (continued). "The feasibility of this concept has recently been proven in an immunohistochemical investigation on the prognostic effect of XIAP and XAF1 in gastric cancer." (PMID 19664236, 2009). "Interestingly, in gastric carcinomas the XIAP/Smac mRNA expression ratio was reported to be similar to normal tissue, whereas the XIAP/XAF1 ratio was significantly increased." (PMID 24281211, 2010). "Additionally, a study on human gastric cancer (SGC7901 cells) revealed that betulin prevented cell proliferation and clonogenic growth of gastric cancer cells via activation of intrinsic apoptotic signaling axis by downregulating anti-apoptosis proteins XIAP and Bcl-2." (PMID 37509141, 2023). "YM155 also inhibited the expression of XIAP in pancreatic and gastric cancer cell lines, except for MKN45 cells; in these cells, YM155 had no discernable effect on XIAP levels." (PMID 22723871, 2012). "cIAP2 (but not cIAP1 and XIAP) was found to be expressed at a higher level in well-differentiated gastric cancer cell lines (MKN7, MKN74 and NCI-N87) than in moderately (SGC-7901) or poorly differentiated gastric cancer cells (SNU-1, AGS), at the mRNA level." (PMID 33825941, 2021).
glioblastoma (23 papers, 2005 to 2025). The most malignant astrocytic tumor (WHO grade IV). "Especially it has been reported that XIAP is overexpressed in glioblastoma, and it is supposed to be associated with drug resistance and poor prognosis of these patients." (PMID 23826488, 2013). "Translation of IRES-containing mRNAs, which encode anti-apoptotic proteins such as XIAP, Bcl-xL, and Cellular Inhibitor of Apoptosis Protein 1 (cIAP1) as well as Nuclear factor erythroid 2-related factor 2 (Nrf2), are regulated by eIF5B in glioblastoma multiforme (GBM) cells." (PMID 34512736, 2021). "In a radioresistant glioblastoma cell line, XIAP inhibitors favored apoptosis induced by gamma-irradiation." (PMID 33477367, 2021). "XIAP is upregulated in glioblastoma, and XIAP inhibitor has been shown effective to treat glioblastoma tumorspheres in vitro." (PMID 34319007, 2021). "XIAP proteins play a key role in regulating apoptosis in CSCs and are expressed at higher levels in glioblastoma and nasopharyngeal carcinoma stem cells." (PMID 33477367, 2021). "In previous studies, inhibition of 5-LOX induced inhibition of proliferation and down-regulation of XIAP in human glioblastoma cells." (PMID 29290980, 2017). "The anti-glioblastoma activity of saponin 1 was characterized by a significant inhibition of NF-κB with a subsequent down-regulation of survivin and XIAP." (PMID 24278406, 2013). "It is clear from GBM cell line studies that targeting of IAPs sensitizes cells to apoptosis and a recent report showed that XIAP inhibitors synergizes with radiation to increase glioblastoma cell apoptosis." (PMID 20515495, 2010). "The RING finger domain of XIAP is capable of interacting with the BIR2 and BIR3 domain of cIAP2 and this XIAP-cIAP2 complexation upregulates the protein stability of cIAP2 in glioblastoma cells." (PMID 32019552, 2020). "A Western blotting technique was validated using a GST–XIAP fusion protein as a standard and HeLa cells and SF268 (human glioblastoma) cells as high and low XIAP expression QCs." (PMID 15685240, 2005). "Through suppression of several oncogenes including p-AKT, EZH2, XIAP, CDK6, cyclin-D1 and cyclin-D2, overexpression of miR-340 inhibits cancer cell proliferation, migration and invasion, induces apoptosis and autophagy in glioblastoma and miR-340 is a marker for glioblastoma diagnosis and prognosis." (PMID 27036021, 2016).
Immunodeficiency (23 papers, 2013 to 2025). Failure of the immune system to protect the body adequately from infection, due to the absence or insufficiency of some component process or substance. "A rare form of immunodeficiency often resulting in HLH is the deficiency of X-linked Inhibitor of Apoptosis (XIAP), induced by alterations in the XIAP/BIRC4 gene." (PMID 37426667, 2023). "The possibility remains, though, that this is a risk allele for immune disorders, in combination with XIAP hemizygosity in P69, and an as yet unidentified cofactor in this case of VEOIBD." (PMID 35743704, 2022). "Sequencing of his entire genome and DNA variant analysis yielded an answer, immunodeficiency due to a pathogenic variant in the XIAP gene." (PMID 34350142, 2021). "A default in NOD1/2-dependent immune signaling had been detected in XLP2 (X-linked lymphoproliferative syndrome type-2) that is an immunodeficiency disease linked to inactivating mutation in the XIAP gene." (PMID 32365919, 2020). "XIAP (X‐linked IAP) is indispensable for NOD2 signaling and familial mutations in XIAP that impact on its function cause severe immunodeficiency with variable clinical presentation, including early‐onset chronic colitis in ~20% of afflicted individuals." (PMID 30026309, 2018). "We also demonstrated the correlation of disrupted gene XIAP in an inversion breakpoint to be causative for the patient’s immunodeficiency phenotype." (PMID 24603971, 2014). "The X-linked lymphoproliferative syndrome type-2 is an immunodeficiency disease caused by mutations in the XIAP gene." (PMID 23818254, 2013). "Among them, XIAP is the causative gene for the immunodeficiency phenotype seen in the patient." (PMID 24603971, 2014). "In humans, inactivating mutations of XIAP result in X-linked lymphoproliferative disease-2 (XLP-2) which is characterized by a state of lymphoproliferation and immunodeficiency, but the mechanisms are not fully understood." (PMID 37347786, 2023). "IL-18 production is a hallmark of several monogenic immunodeficiencies that produce IBD symptoms, including macrophage activation syndrome (MAS) secondary to NLRC4 mutation, as well as mutations in X-linked inhibitor of apoptosis (XIAP)." (PMID 36986830, 2023). "A likely pathogenic variant in XIAP (p.R443P) was identified in a 6-year-old girl with HLH, recurrent EBV infections, and suspected underlying immunodeficiency." (PMID 28007021, 2016). "Several immunodeficiency disorders associated with EBV lymphoproliferation have been described, including deficiency of ITK, XIAP, STK4, SH2D1A, and CD27." (PMID 27338827, 2016). "The inversion breakpoint disrupted XIAP gene, which is the primary cause of a rare form of XLP2 (XLP2 [MIM: 300635]) and likely to be causative for the immunodeficiency phenotype of the patient." (PMID 24603971, 2014). "Mutations in XIAP cause X-linked lymphoproliferative syndrome type-2 (XLP2), an immunodeficiency associated with a potentially fatal deregulation of the immune system, whose aetiology is not well understood." (PMID 23818254, 2013). "Poor development of memory T cell response due to inactivation of XIAP could result in a state of immunodeficiency." (PMID 37347786, 2023). "In I. scapularis, the x-linked inhibitor of apoptosis protein (XIAP) interacts with the E2 conjugating enzyme Bendless affecting positive and negative regulators of the immune deficiency (IMD) pathway resulting in protection against infection by A. phagocytophilum." (PMID 28439499, 2017). "Taken together, these results indicate that a deficiency of XIAP while promoting cycling and effector function of CD8 T cells initially compromises the ability of primed CD8 T cells to develop into memory cells which results in poor control of infection, thereby creating a state of immunodeficiency." (PMID 37347786, 2023).
Immunodeficiency (continued). "Since no diagnostic details are given, the exclusion of combined immune deficiencies involving T-cell immunity as well as B-cell failure, or known mutations in monogenic disease (e.g. CTLA4, LRBA, KMT2D, XIAP, RAG1, NFKB1) is unclear." (PMID 33329602, 2020). "Considering the normal expression of SAP protein and the absence of functional gene expression of XIAP, these data clearly suggest that XLP-2 underlies the immunodeficiency symptoms of the affected twin boys." (PMID 24603971, 2014).